AFP (alpha fetoprotein)
Diseases named in the same sentence as AFP in open-access papers (continued):
Sharing a sentence is not in itself a finding about the gene and the disease.
tumor (continued). "Irreversible electroporation of tumor cells combined with allogeneic NK cell immunotherapy significantly increases the overall survival of patients with stage IV HCC and this combinatorial approach had synergistic effect by reduction of AFP levels with clinical benefit." (PMID 34071188, 2021). "Similarly, our study demonstrated that AFP was also significantly associated with MVI presence, but the tumor number did not seem to be an independent risk factor of MVI." (PMID 35096577, 2021). "However, KIAA0101 protein levels in HCC tissues were not correlated with patient age, tumor size, serum AFP level, or the HBsAg expression." (PMID 33743635, 2021). "We investigated the role of tumor markers AFP response or DCP response, which may not be proper prognostic factors." (PMID 33877527, 2021). "However, there were no statistical significance in age, gender, HBsAg, tumor number, alpha-fetoprotein (AFP), vascular invasion, BCLC stage, differentiation, PT, ALT, GGT, and ALB." (PMID 33906632, 2021). "no tumor was found radiologically, and the AFP values were reduced to normal." (PMID 34737958, 2021). "In order to confirm these observations further, pieces of tumor and peri-tumoral tissue that did not contain tumor (stem) cells were placed on G0 for 32 days, then removed, and the attached cells were stained for AFP (green) and α-SMA (red)." (PMID 34947582, 2021). "Indeed, exceeding AFP score at diagnosis or at listing was not predictive of tumor recurrence but the last AFP score at imaging and that at the explant analysis were predictive." (PMID 34069594, 2021). "However, another recent study indicated that more than 0.7-cm surgical margin was important to prevent early recurrence among HCC patients with MVI, no tumor capsule and alpha-fetoprotein (AFP) levels ≥100 ng/ml." (PMID 34123861, 2021). "The AFP level is known to improve the screening-based detection of HCC and the combination of image-based radiomic features with clinical parameters such as Child-Pugh score, tumor size or AFP level has already been established to improve the prediction of survival." (PMID 34573991, 2021). "Classical tumor markers also followed the same tendency, with the decrease in proportion of positive cases for AFP in stage II being explained by the high proportion of SE (which are AFP-negative) in the stage II group (56.5%)." (PMID 34680375, 2021). "Following discussion with the local Urology service, assessment of tumor markers was performed, which revealed elevated lactate dehydrogenase (LDH) at 449 U/L (reference range 0–250 U/L) with beta human chorionic gonadotropin (hCG) and alpha fetoprotein (AFP) within the normal range." (PMID 34281593, 2021). "At 12–24 h, the SNR of tumors treated with MPDA@SPIO/SA-PEI/AFP-Fth nano preparations was still weakening, and the tumor slices were in 24 h showed SNR=25.2, when ferritin expression reached the level required for measurable T2W1 effect, Fth reporter gene with AFP promoter could be worked." (PMID 34819084, 2021). "In GCTs, β-HCG (β subunit of human chorionic gonadotropin), AFP (alpha-fetoprotein), and LDH (lactate dehydrogenase) are clinically used as serum markers to diagnose tumors but have limitations in sensitivity and specificity, especially in certain tumor subtypes, such as SE and EC." (PMID 34575133, 2021). "The patient was negative for all tumor markers, including AFP, CEA and PIVKA-II." (PMID 34542724, 2021). "Our study shows that there was no better agreement for the AFP criteria on the explant since the implementation of the AFP model, with 87.5% during the MilanCP compared to 88.2% during the AFPscP (considering viable tumor only)." (PMID 34069594, 2021). "We found that patients with high expression of PAR2 were associated with advanced tumor-node-metastasis (TNM) stage (p = 0.005), and relative high serum AFP level (p = 0.060), but not with other characteristics such as gender, age, etiology, tumor, size, vascular invasion, and pathological stage." (PMID 34199695, 2021).
tumor (continued). "Today, treatment allocation is not guided by any particular tumor characteristic, since no biomarker can effectively predict the response to a particular drug; the only exceptions, at present, are AFP and ramucirumab (anti-Vascular Endothelial Growth Factor Receptor-2 monoclonal antibody)." (PMID 34503144, 2021). "Moreover, the Tumor (T) staging (P = 0.004), Nodule (N) staging (P = 0.008), and Tumor-Nodule-Metastasis (TNM) staging (P = 0.001), was well as AFP (P < 0.001) and Ki67 (P < 0.001) expression rates, and mortality (P < 0.001) were markedly higher in the EWSR1 overexpression group." (PMID 34612781, 2021). "Tumor markers, including AFP, CA19-9 and CEA, are usually not elevated." (PMID 33827427, 2021). "This study showed that, unlike AFP levels, the ssDNA levels began to decline after reaching a peak 3 days after surgery, which might reflect a rapid release of circulating tumor DNA after resection." (PMID 34394775, 2021). "In addition, most laboratory indicators are negative, such as liver function and tumor markers (e.g., alpha-fetoprotein and carcinoembryonic antigen)." (PMID 34918699, 2021). "However, AFP is not always reliable for predicting patient outcomes, tumor differentiation, or malignancy." (PMID 32932781, 2020). "For example, a patient with an albumin of 45 g/L, a bilirubin of 7 μmol/L, an AFP of 5789 U/L, the largest tumour measuring 5.9 cm with macrovascular invasion, but without extrahepatic spread, will have a predicted survival of 87%, 70%, 44% and 19% and 9% at 3, 6, 12, 24 and 36 months, respectively." (PMID 31579990, 2020). "Serum AFP is frequently measured in routine clinical practice, not only for diagnosis or pre-treatment prognostication but also for prediction of treatment response, because it is thought to constantly reflect tumor burden and biology." (PMID 33277619, 2020). "However, it was not correlated with gender (P = .8938), age (P = .5256), tumor size (P = .2130), AFP level (P = .0901), and metastasis (P = .1968)." (PMID 32125733, 2020). "However, unlike AFP, the MethylHBV5k level was not affected by the presence of inflammation, hence making it a more specific tumor marker." (PMID 32741373, 2020). "Tumor metastasis in AFP-negative HCC and AFP-positive HCC patients." (PMID 33014866, 2020). "However, AFP is also elevated in non-tumor environments and is not particularly sensitive for small tumors." (PMID 33134551, 2020). "Serum AFP was not correlated with tumor size, T stage, N stage, and M stage (P > .05)." (PMID 31881123, 2020). "Moreover, a similar effect of AFP was detected in tumour tissues with high serum AFP, but not in adjacent non‐cancerous liver tissues, or HCC tissues with low serum AFP levels." (PMID 33090723, 2020). "As in AFP and GPC3 detection, ATAD2 may become a prospective molecular biomarker, allowing for the early diagnosis and treatment of HCC patients, thereby avoiding the adverse effects of tumor progression." (PMID 32462022, 2020). "At the tumor level, those treated with proton radiotherapy had an earlier clinical AJCC stage (40.6% vs. 9.2% for stage I/II and 31.6% vs. 79.9% for stage III, p < 0.001), lower AFP level (54.7% vs. 36.4% for AFP < = 200 ng/mL, p < 0.001), and fewer cases of PVTT (37.5% vs. 78.8%, p < 0.001)." (PMID 32605627, 2020). "Aggressiveness Index (AgI) is a recently introduced scoring system for HCC tumor patterns which takes accounts of four tumor-related parameters i.e., maximum tumor diameter (MTD), number of tumor nodules, portal vein thrombosis (PVT) and serum alpha-fetoprotein (AFP) level." (PMID 32508980, 2020). "Interestingly, patients with either elevated AFP or GGT had larger tumor diameters than that of those with lower AFP and GGT, smaller than that of patients with both elevated AFP and GGT, indicating the positive correlation between A-G score and tumor size." (PMID 32850396, 2020).
tumor (continued). "In this study, the authors proposed a new selection criteria for LDLT with a scoring model including the number of nodules (less or equal than 5), largest tumor diameter less or equal than 50 mm and the presence/absence of AFP >250 ng/mL, DCP >450 mAU/mL (LDLT Tokio University criteria)." (PMID 32492896, 2020). "Even though tumor size, AFP, and ICG-15 individually may not be adequate in distinguishing the presence of VI, formate appeared to display an acceptable AUROC of 0.612 in the investigation group and 0.727 in the validation group." (PMID 32493393, 2020). "However, this score was not related with age, gender, ALT serum level, AFP concentration, tumor capsule and Child-Pugh grade." (PMID 31598154, 2019). "Thus, the clinical-radiological nomogram was constructed including the AFP level, gross vascular invasion and non-smooth tumour margin." (PMID 31088553, 2019). "Studies on non dysgerminomatous tumors suggest, an early stage minimal residual tumor after the initial surgery, less than 100 ml of ascites, platinum-based chemotherapy, an AFP level less than 1,000 kU/L, and a non-EST histology were found to be significantly related to a more favorable prognosis." (PMID 31897390, 2019). "In conclusion, elevated preoperative serum CA125 predicted larger tumor diameter and poor prognosis after patients with HCC with AFP ≤200 ng/mL underwent R0 resection, which may be explained by the elevation of the preoperative serum CA125 level significantly associated with MTD>5 cm." (PMID 31662990, 2019). "According to the well-established 400 ng/ml cut-off, only 12% (29/244) of patients with early HCC presented high serum levels of AFP, which was accompanied by aberrant overexpression of the gene in the tumour (FC = 40; p < 0.001) compared with the adjacent non-tumoral tissue." (PMID 31285588, 2019). "When all mice reached 13 months old, HBs-Tg mice with H. hepaticus administration involved in hepatic neoplasia development with a higher incidence (100%), more tumor nodules (P < 0.01) and higher serum AFP (P < 0.01), compared to wild type B6 with or without H. hepaticus and HBs-Tg mice." (PMID 31123503, 2019). "AFP-levels increased significantly with increasing tumour size in nonseminoma." (PMID 31275973, 2019). "Similarly, in our results, AFP was associated with OS and PFS in these 272 patients with HCC (TS ≤ 5 cm), but there was no prognostic meaning for AFP in the HCC patients with tumor size ≤ 3 cm or ≤ 2 cm." (PMID 31165038, 2019). "The levels of AFP did not demonstrate any clear pattern relative to overall tumor response." (PMID 29995286, 2019). "In summary, our findings suggest that patients with HCC who have higher BMI, normal liver function, lower AFP level, the absence of vascular invasion, smaller tumor size, and solitary tumors may have a better outcome after TACE." (PMID 31313476, 2019). "AFP is the most widely used tumor marker, but its sensitivity and specificity is not sufficient." (PMID 33817137, 2019). "However, other clinical characteristics, including age, sex, serum alpha fetoprotein, Child-Pugh score, tumor number, tumor capsulation and differentiation were not directly related to the expression of Mortalin." (PMID 31772652, 2019). "However, a clear understanding of the mechanisms of AFP overexpression and the molecular traits of patients with AFP-high tumours are not known." (PMID 31285588, 2019). "Therefore, we hypothesize that serum AFP not only is involved in the initiation of HAS, but also plays important roles in tumour progression and invasion." (PMID 30989433, 2019). "It is noted that one patient with a large tumor at recurrence (5.5 cm lesion) was AFP negative (AFP value of 6.2 ng/mL) at the time of diagnosis, which may explain this person’s late diagnosis." (PMID 30169533, 2018).
tumor (continued). "Tumour size > 7 cm (p < 0.001), intra-tumour necrosis (ITN) (p = 0.02) and arterial ectatic neovascularisation (AEN) (p = 0.03) emerged as individual prognostic factors together with radiologic response (p < 0.001) and elevated alpha-fetoprotein (AFP) (p = 0.01)." (PMID 29463228, 2018). "Using this method, we found that tumor DNA-PKcs expression was significantly associated with the HBs Ag status (positive/negative), presence/absence of portal vein invasion, size of the largest tumor nodule (≤3.0 cm/>3.0, cm), serum AFP level (ng/mL), and the postoperative outcomes." (PMID 30301934, 2018). "AFP, CEA, CA19-9, and other tumor markers have no specific diagnostic value in both groups." (PMID 30416612, 2018). "Further, it indicates that biopsy could be still indicated in case of suspected HCC in cirrhotic patients, particularly in the presence of unusual findings such as the combination of a FDG PET scan positive tumor in the absence of elevated alpha-fetoprotein." (PMID 29850362, 2018). "However, excessive elevation in liver function markers along with total bilirubin and alpha-fetoprotein, a prominent tumor marker (data not shown) confirms severe liver toxicity and damage akin to hepatocarcinoma in the present study." (PMID 29374195, 2018). "In addition, serum tumor marker levels decreased to normal range: CEA, 2.0 ng/ml; AFP, 3.7 ng/ml." (PMID 30191347, 2018). "Last, the abnormally elevated tumor marker AFP was only seen in HCC but not in Epi-HAML." (PMID 30619742, 2018). "In line with this hypothesis, a recent report in HCC identified an AFP-peptide (AFP-158)-specific T cell receptor (TCR) that promotes dramatic activity in in vitro and in vivo tumor models and the development of AFP-targeted chimeric antigen receptor therapy is underway." (PMID 30208947, 2018). "Serum neurotensin, a new tumour marker for FHCC may discriminate it from HCC especially as a negative or normal value of alpha fetoprotein (AFP) tumour marker does not exclude an HCC." (PMID 30305894, 2018). "We observed a negative correlation between GSTP1 expression and both tumor size and serum AFP." (PMID 29507666, 2018). "Large/multifocal HCC patients with poor tumor response, higher baseline AFP level, and AFP decrease less than 50% before HR might not be suitable for HR after TACE." (PMID 27880724, 2017). "These classifications of the BCLC staging classification, JSH algorithm, and Japanese evidence-based treatment algorithm rely on tumor morphologic factors and not biomarkers such as alpha-fetoprotein (AFP) and protein induced by vitamin K absence or antagonism factor II (PIVKA-II)." (PMID 28830473, 2017). "Besides, the serum AFP of this patient was in the normal level and his immunohistochemical results showed negative AFP expression in the tumor." (PMID 29310401, 2017). "However, TNM stage, liver metastasis, serum AFP level, and tumor AFP or CEA immunoreactivity did not present a correlation with these subtypes." (PMID 28423604, 2017). "However, as serum AFP is also related to the altered hepatocyte architectures in CHC, rapid normalization of serum AFP after IFN-free DAAs could be misleading; cautious re-evaluation of this useful clinical tumor marker is needed." (PMID 28617830, 2017). "Furthermore, we demonstrated that positive expression of HSP90 and PKM2 was correlated with poor clinicopathological features including high alpha fetoprotein (AFP) level, large tumor size, portal vein tumor thrombus (PVTT) and advanced tumor-node-metastasis (TNM) stage." (PMID 29262861, 2017). "Tumor size (HR = 1.27, 95% CI: 1.15–1.40), HBV-DNA (HR = 7.70, 95% CI 3.57–16.63), AFP levels before treatment (HR = 2.172, 95% CI 1.256–3.756, P = 0.006), and AFP response (HR = 4.722, 95% CI 1.053–21.184, P = 0.0427) were independently associated with the risk of recurrence of HCC after RFA." (PMID 28679433, 2017).
tumor (continued). "However, to date the efficacy of adding another tumor maker to a surveillance program with US and AFP has not been fully assessed, especially in terms of cost-effectiveness." (PMID 28620797, 2017). "The patients with AFP-positive with unfavorable tumor phenotypes may explain why AFP-positive did not confer a survival benefit after surgery compared with patients with AFP-negative." (PMID 28993684, 2017). "However, NAT10 expression did not correlate significantly with age, α-fetoprotein (AFP) levels, capsular formation, tumor number, margin status and Edmondson-Steiner grade." (PMID 28859621, 2017). "Therefore, a precise biomarker for HCC is needed to predict the prognoses of patients with a smaller tumor size who are AFP negative." (PMID 28122351, 2017). "Furthermore, the expression of SART3 was detected in the HCC tissue of all patients, and was independent of the expression of AFP in the tumor." (PMID 28114424, 2017). "AFP, number of nodules, and tumor cell differentiation was similar between non-SN and SN types." (PMID 28392502, 2017). "The mRNA expression of PLCE1and AFP (Affymetrix Probe Set IDs: 205112_at and 204694_at, respectively) differed between HCC and adjacent normal tissues in these patients (P < 0.001), and the latter also differed in tumor tissues of the various serum AFP subgroups (P < 0.001)." (PMID 28418898, 2017). "Despite this in both aetiologies, patients in Japan clearly survived longer than those in Hong Kong and multivariable analysis showed that tumour-related factors, such as vascular invasion, AFP and tumour size, but not aetiology, accounted for these differences." (PMID 28081537, 2017). "The reasons why AFP, tumour size, pathology grade are not independent predictors for HCC may be due to the effects of multiple collinearity and the small sample size." (PMID 28899352, 2017). "Pre-operative serum AFP levels could not represent any tumors’ characteristics such as tumor size, disease stage, and pathological status." (PMID 29254216, 2017). "Furthermore, our findings revealed that high levels of peripheral AFP did not reflect the degree of tumor invasion in pathology." (PMID 29254216, 2017). "After adjusting for Child–Pugh score, radical resection, antiviral therapy after hepatectomy, tumor size and number, BCLC stage, PVTT, and regional invasion in the Cox proportional hazards regression model, the MST was similar among patients with different AFP levels and haplotypes." (PMID 28418898, 2017). "Although the AFP level was within the normal range, we speculate that the reason for this finding was that the tumor had not yet undergone malignant transformation." (PMID 29381973, 2017). "Correlations between AFP and tumor/circulating MET were not meaningful." (PMID 27579536, 2016). "Similarly, gender, Edmondson grade, tumor size, TNM stage, serum AFP, and PON3 expression level could be predictor for OS." (PMID 27661119, 2016). "In the 1980s, ultrasound examination together with AFP testing has been gradually popularized as a PLC screening method in the endemic areas in China, which led to a large number of asymptomatic cases of PLC found and more frequent neoplasms identified from cirrhotic patients." (PMID 27733148, 2016). "However, some promoters, such as cytomegalovirus and Simian virus 40, do not have tumor specificity, whereas others, such as alpha-fetoprotein, carcinoembryonic antigen and prostate-specific antigen promoters, show strong specificity only in certain tumors." (PMID 27283901, 2016). "Out of 286 proteins studied, 119 were detected in all 77 tumor samples (32 AFP producing and 45 AFP non-producing), and 11 of 119 proteins were found to be differentially expressed between the two groups based on the unpaired t test and SAM analysis (p<0.05 and q<5%)." (PMID 27057629, 2016). "Thus, AFP is likely to be a marker of tumor cell de-differentiation rather than a marker of hepatic metastases from NETs." (PMID 26976278, 2016).